RN7SL91P (RNA, 7SL, cytoplasmic 91, pseudogene)
Gene: Miscellaneous RNA gene on chromosome X (25,060,649 to 25,060,939, reverse strand). Ensembl gene ENSG00000240439.
Homologues: Orthologues: chimpanzee Metazoa_SRP (99% identical), macaque Metazoa_SRP (93% identical). Paralogues in human: RN7SL1 (87% identical), RN7SL3 (86% identical), RN7SL2 (86% identical), RN7SL448P (86% identical), RN7SL650P (84% identical), RN7SL709P (84% identical), RN7SL126P (83% identical), RN7SL197P (83% identical), RN7SL464P (83% identical), RN7SL493P (83% identical), RN7SL652P (83% identical), RN7SL803P (83% identical), and 703 more.